DOK7 (docking protein 7)
Diseases named in the same sentence as DOK7 in open-access papers (continued):
Sharing a sentence is not in itself a finding about the gene and the disease.
bladder cancer (2 papers, 2023). "To further verify the functions of DOK7 in bladder cancer, we used siRNA to knockdown the expression of DOK7." (PMID 36709279, 2023). "Consistently, with the knockdown of DOK7, bladder cancer cell proliferation and migration abilities were promoted." (PMID 36709279, 2023). "In our study, DOK7 was chosen to further verify our prognosis model, and functional assays indicated that knockdown the expression of DOK7 could prompt bladder cancer proliferation and migration." (PMID 36709279, 2023). "Based on that found, we thought that DOK7 may also could prompt or inhibit bladder cancer." (PMID 36709279, 2023). "Five genes in our prognostic model, ANXA1, MAP1B and SPOCD1 have been reported in bladder cancer, however DOK7 and FKBP10 has not been studied in bladder cancer." (PMID 36709279, 2023).
leukemia (2 papers, 2019 to 2021). A malignant (clonal) hematologic disorder, involving hematopoietic stem cells and characterized by the presence of primitive or atypical myeloid or lymphoid cells in the bone marrow and the blood. "DOK7 belonged to a family of docking protein and DOK7 inhibited malignant cell proliferation and increased leukemia patient survival." (PMID 31443559, 2019).
lymph node metastasis (2 papers, 2021 to 2023). "Through univariate COX regression analysis, we found that DOK7 expression level, tumor depth, lymph node metastasis, distant metastasis, and the clinical stages showed statistically difference (P < 0.05)." (PMID 38095644, 2023). "Furthermore, patients with the high lymph node metastasis (N1/2/3) group had lower expression of DOK7 than that of the low lymph node metastasis (N0)." (PMID 33552156, 2021).
motor neuron disease (2 papers, 2017 to 2023). "Our findings demonstrate that DOK7 gene therapy has potential for treating various motor neuron diseases that manifest NMJ defects." (PMID 28490573, 2017). "However, DOK7 gene therapy has not previously been demonstrated to be effective in motor neuron diseases." (PMID 28490573, 2017).
myasthenia gravis (2 papers, 2016 to 2020). Myasthenia gravis (MG) is a rare, clinically heterogeneous, autoimmune disorder of the neuromuscular junction characterized by fatigable weakness of voluntary muscles. "Mutations in Dok7 lead to the disease myasthenia gravis, indicating that Dok7 plays a key role in the activation of MuSK." (PMID 27459095, 2016).
age (1 paper, 2020). A temporal measurement of the time period elapsed since an identifiable point in the life cycle of an organism. "However, the effect of DOK7 gene therapy on age-related motor dysfunction was unknown." (PMID 32758427, 2020).
Atrophy (1 paper, 2023). Any weakening or degeneration, especially through lack of use. "The activation of the muscle-specific kinase MuSK by the cytoplasmic protein Dok-7 is essential for NMJ formation, and Dok-7 recovery reduces muscle atrophy in a SOD1-G93A transgenic mouse model." (PMID 35691950, 2023).
breast tumors (1 paper, 2016). "The relationship between hormone receptor status and promoter methylation of DOK7 and ELF5 was further examined using available methylation array data (Illumina HM450) from a set of paired primary and second breast tumors from 24 women." (PMID 26884724, 2016). "To extend these findings clinically, we examined the relationship between hormone receptor status, anti-estrogen treatment and promoter methylation of DOK7 and ELF5 in a set of matched primary and recurrent breast tumors from 24 women." (PMID 26884724, 2016). "This study characterizes the expression of hormone receptors, and the mRNA and DNA methylation levels of docking protein 7 (DOK7), and E74-like factor 5 (ELF5), in 21 novel tamoxifen-resistant cell lines and extends the findings to primary and recurrent human breast tumors." (PMID 26884724, 2016).
Escobar syndrome (1 paper, 2022). "While CHRNG mutations caused Escobar syndrome for 75 patients of known cases, a number of patients had a genetic etiology associated with variants in the TPM2, CHRND, CHRNA1, MUSK, MYH3, RAPSN, and DOK7 genes." (PMID 36292632, 2022).
Hepatic steatosis (1 paper, 2019). Steatosis is a term used to denote lipid accumulation within hepatocytes. "We found that exonic and intronic CpG islands in DOK7 were hypomethylated by OA and hypermethylated by EAT, and that expression of the gene was decreased by OA and elevated by EAT in our cell model of hepatic steatosis." (PMID 31170227, 2019).
meningioma (1 paper, 2022). A generally slow growing tumor attached to the dura mater. "Candidates such as DOK7 (3 hits, NC), the PCDH clusters (32 hits, PC), PAX6 (15 hits, PC), and TBR1 (6 hits, PC), among others with dynamic and island-restricted CpGs, constitute potential proliferative biomarkers in meningiomas." (PMID 36551712, 2022). "When considering mitotic activity in meningiomas, we found negative correlations with DNAm for ARHGDIA and DOK7 and positive correlations for ESRRG and OTX1 (both correlating with all proliferation indices)." (PMID 36551712, 2022).
metabolic syndrome (1 paper, 2019). A cluster of metabolic risk factors for CARDIOVASCULAR DISEASES and TYPE 2 DIABETES MELLITUS. "We investigated the correlation of DNA methylation with expression of seven genes (WDR27, GNAS, DOK7, EDN3, CMYA5, PRKG1, and MCF2L) selected on the basis of their known functions in metabolic syndrome, and their locations in functional genomic regions." (PMID 31170227, 2019). "Seven genes (WDR27, GNAS, DOK7, EDN3, MCF2L, PRKG1, and CMYA5) were selected based on genomic location and relevance to metabolic syndrome." (PMID 31170227, 2019).
scoliosis (1 paper, 2023). A congenital or acquired spinal deformity characterized by lateral curvature of the spine. "Skeletal deformities, such as scoliosis, are more commonly encountered in syndromes with DOK7 mutations, typically manifesting as normal early motor development and eye movement after the age of two." (PMID 37766777, 2023).
Stroke (1 paper, 2022). Sudden impairment of blood flow to a part of the brain due to occlusion or rupture of an artery to the brain. "In the UKB, we attempted to replicate only the PRIM2 rs199585353 and DOK7 rs149905649 associations observed in the European ancestry group as the number of African ancestry individuals in UKB with stroke was small (n = 101)." (PMID 36672803, 2022).
tumor (9 papers, 2014 to 2024). "DOK7 is a docking protein correlate with tumor recurrent and an indicator of cancer risk." (PMID 36709279, 2023). "In the clinical samples, IHC staining and Western blot results revealed that the protein levels of DOK7 in para-cancerous normal tissues were significantly higher compared to the tumor tissues." (PMID 38095644, 2023). "The monitoring of the tumor growth and tumor weight showed that DOK7 overexpression significantly suppressed the tumorigenesis of T24 cells in nude mice." (PMID 38095644, 2023). "RT-qPCR results showed that DOK7 mRNA expression levels in the para-cancerous tissues were significantly higher in comparison to BLCA tumor tissues." (PMID 38095644, 2023). "Collectively, our data suggest that DOK7 serves as a tumor suppressor to impair the aggressive phenotype in BLCA cells." (PMID 38095644, 2023). "IHC staining of the tumor tissues showed that the high level of DOK7 expression significantly reduced the levels of the proliferating maker Ki-67." (PMID 38095644, 2023). "DOK7 expression was significantly down-regulated in BLCA tumor tissues of more advanced clinical stages." (PMID 38095644, 2023). "Together, these data support that DOK7 serves as a tumor suppressor in BLCA possibly by targeting JAK signaling pathway." (PMID 38095644, 2023). "Several studies suggested DOK7 as a potential tumor-suppressor gene, because of the significantly low expression levels in BC tissues compared with normal tissues." (PMID 37875600, 2023). "The downstream of tyrosine kinase (DOK) family is composed of seven members, DOK1 to DOK7, and some of them have the effects on the negative regulation of tumor signaling pathways." (PMID 33552156, 2021). "To investigate the molecular mechanisms how DOK7 expression mediated tumor growth and metastasis, we checked PI3K/PTEN/AKT pathway-associated proteins in DOK7-overexpressed or controlled MDA-MB-231 and SKBR3 cells." (PMID 33552156, 2021). "DOK7 serves as a tumor suppressor which was down-regulated in BLCA tumor and cells." (PMID 38095644, 2023). "Emerging evidence suggests that DOK7 functions as a tumor suppressor in different cancers." (PMID 38095644, 2023). "In this present study, we identified DOK7 as a potential tumor suppressor in BLCA." (PMID 38095644, 2023). "In addition, overexpression of DOK7 suppressed tumor proliferation and lung metastasis in animal models." (PMID 33552156, 2021). "Similarly, DOK7 mRNA expression was significantly reduced in large tumors (T1 stage, tumor diameter >2 cm) compared with tumors with the diameter ≤2 cm (T2/3 stage)." (PMID 33552156, 2021). "Additionally, expression and methylation of docking protein 7 (DOK7) were measured due to the protein’s potential role as a tumor suppressor." (PMID 26884724, 2016). "Interestingly, the methylation of DOK7 was also found in samples taken, on average, 4.7 years before tumor diagnosis, implying that the epigenetic change occurs early in the development of the disease." (PMID 25484923, 2014). "In addition, DOK7 overexpression also reduced the levels of p-JAK1, p-JAK2 and p-JAK3 in the tumor tissues." (PMID 38095644, 2023). "Interestingly, overexpression of DOK7 restrained cell proliferation both in MDA-MB-231 and SKBR3 cells, while repression of PTEN expression using PTEN siRNA or SF1670 (PTEN inhibitor) rescued the tumor-inhibiting effect induced by DOK7 overexpression." (PMID 33552156, 2021).
cancer (7 papers, 2017 to 2025). A tumor composed of atypical neoplastic, often pleomorphic cells that invade other tissues. "Together, our data and previous studies support the notion that targeting DOK7 could be a strategy to mitigate the aggressiveness of cancer cells in different malignancies." (PMID 38095644, 2023). "Other genes, such as ALOXE3, HBQ1, KREMEN2, SYT13, DOK7, CDC5L, and FBXO6, have been reported in several cancers." (PMID 28404969, 2017).
neuromuscular disease (5 papers, 2015 to 2024). "The muscle protein Dok-7 is essential for activation of the receptor kinase MuSK, which governs NMJ formation, and DOK7 mutations underlie familial limb-girdle myasthenia (DOK7 myasthenia), a neuromuscular disease characterized by small NMJs." (PMID 26230713, 2015).
metabolic disease (1 paper, 2019). A congenital disorder (due to inherited enzyme abnormality) or acquired (due to failure of a metabolically important organ) disorder resulting from an abnormal metabolic process. "It was reported that DOK7 plays a crucial role in the progress of metabolic disease in an animal model through regulation of DNA methylation at its promoter, affecting its expression." (PMID 31170227, 2019).
DOK7 also shares sentences with these, for which no sentence is quoted: Emery-Dreifuss muscular dystrophy (3 papers); myopathy (3); neurodegenerative disease (2); spinal muscular atrophy (2); acute myeloid leukemia (1); arthrogryposis (1); channelopathies (1); fetal akinesia deformation sequence (1); gastric cancer (1); genetic disorders (1); infection (1); Lambert-Eaton myasthenic syndrome (1); limb girdle muscular dystrophy type 2A (1); mitral valve prolapse (1); muscular disease (1); non-small cell lung carcinoma (1); Obesity (1); ophthalmoplegia (1); ptosis (1); Stridor (1).